PTPN11 (protein tyrosine phosphatase non-receptor type 11)
Diseases named in the same sentence as PTPN11 in open-access papers (continued):
Sharing a sentence is not in itself a finding about the gene and the disease.
tumor (454 papers, 2009 to 2026). "Paired exome analysis of disease-involved tissue (estimated 30% tumor content) and a comparator sample revealed a germline missense variant in PTPN11 p.Lys70Arg (classified as expert panel pathogenic in ClinVar, variation ID: 44603)." (PMID 39309743, 2024). "Inthis study, we conducted comprehensive examination of gene expression profiles,transcriptional factor regulons, and cell compositions/interactions throughout variousstages of tumor cell development in Ptpn11 mutation-associated JMML." (PMID 39149498, 2024). "Paired exome sequencing (estimated 70% tumor content) identified a pathogenic missense hotspot variant in PTPN11 p.Asn308Asp (classified as expert panel pathogenic in ClinVar, variation ID: 13326)." (PMID 39309743, 2024). "Improved control of tumour growth in mice with myeloid-specific Ptpn11-deficiency was associated with decreased myeloid-derived suppressor cell activity and enhanced activation of tumour-infiltrating T cells." (PMID 38334623, 2024). "In brain tissue from the patient with LEAT associated with PTPN11 p.G503V, we observed substantial correlation between tumor density and the degree of pErk1/2 staining, supporting the validity of this strategy in localizing variant-positive cells." (PMID 37126322, 2023). "We conducted a survival correlation study for every malignancy using a Kaplan-Meier plotter in order to get more insight into the association between PTPN11 expression and prognostic value across diverse tumor types." (PMID 35802774, 2022). "Further, a gene co-expression study was performed to investigate the relationships between the expression of PTPN11 and immune-associated genes and tumor-infiltrating lymphocytes (TILs) across multiple kinds of human tumors." (PMID 35802774, 2022). "In both the previously published case as well as in our presented case, it is unclear if the PTPN11 mutation is a driver alteration linked to the emergence of the neoplasm, or if it is a passenger mutation." (PMID 35484611, 2022). "Given that the VAF of both the FGFR1 and PTPN11 variants were nearly identical in the tumor tissue suggesting that the variants co‐exist in the tumor cells, it is possible that the FGFR1 mutation that initiated the clonal expansion and tumor progression." (PMID 35778969, 2022). "The recurrent tumor displayed a similar low grade-appearing histology and harbored the same H3 K27M and PTPN11 mutations as the primary." (PMID 35484611, 2022). "For example, PTPN11 encodes the tyrosine phosphate SHP2, which is often overactivated in tumour endothelial cells." (PMID 36045675, 2022). "PTPN11 gene was mutated within a tumor that originated within corpus callosum and had highest gene expression in the corpus callosum and cingulum bundle." (PMID 34257334, 2021). "MC38 tumor cells are insensitive to direct inhibition of SHP2 as they carry the G503V mutation of Ptpn11 gene." (PMID 33446805, 2021). "Since somatic mutations in PTPN11 are seen in several tumor types, NS which causes germline PTPN11 mutations are also increase the risk of hematologic malignancies and brain solid tumors." (PMID 31637070, 2019). "These tumours were characterised by increased phosphorylation of several signalling molecules known to associate with erbB2, including Ptpn11, Plcγ1, Cbl and CrkL, as well as its heterodimerisation partner Egfr." (PMID 25200860, 2014). "We identified a PTPN11 variant in all tumours in one patient." (PMID 36882706, 2023). "Taken together, these data strongly indicated that MF was involved in multiple tumor-associated signaling pathways, and, most importantly, that MF may exert its anti-tumor activity by targeting PTPN11." (PMID 37892971, 2023). "The first group (“molecular low-grade”) consisted of those 29 tumors with biallelic inactivation of the NF1 tumor suppressor gene only and one tumor with biallelic inactivation of NF1 plus an activating missense mutation in PTPN11, a phosphatase that regulates the MAP kinase signaling pathway." (PMID 35945463, 2022).
tumor (continued). "Furthermore, there was a significant association between PTPN11 expression and infiltration of cancer-associated fibroblasts and endothelial cells, along with tumor mutation burden, microsatellite instability, mismatch repair genes, and immunoregulators." (PMID 35802774, 2022). "Besides, the PTPN11 expression levels were remarkably related to the invasion of tumor-associated fibroblasts and endothelial cells, as well as TMB, MSI, and MMRs in divergent cancers." (PMID 35802774, 2022). "However, the tumor immune microenvironment is very complex, and the association of PTPN11 with immune cells and how it affects the tumor immune microenvironment remain to be clarified." (PMID 35802774, 2022). "Our results showed that PTPN11 mutations were found in 23/45 (51.1%) of HS tumor samples." (PMID 33441840, 2021). "Identification of the tumour-suppressive miRNA miR-489 and its target, PTPN11, might provide new insights into the underlying molecular mechanisms of HSCC." (PMID 20700123, 2010). "PTPN11 is a pleotropic protein with important functions in cell signalling for proliferation and survival, and PTPN11 dysregulation of tyrosine phosphorylation is associated with several cancers by regulating migration and invasion, tumor microenvironment and cancer immunity." (PMID 39695132, 2024). "Additionally, we assessed whether genetic alterations of PTPN11 was associated with tumor patient survival prospects." (PMID 35802774, 2022). "Theoretically, the case here presented could benefit the most from such treatment, being carrier of two mutations in this cascade, with the somatic PTPN11 variant affecting part of the body—including tumor tissue—and a variant in FGFR1 detected only in tumor tissue." (PMID 35778969, 2022). "Previous research has indicated PTPN11 could bind to the colony-stimulating factor receptor (CSF-1R) complex in response to CSF-1 stimulation in the tumor-associated macrophages to stimulate the Ras/Erk pathway, which can enhance tumor cell proliferation and migration." (PMID 35802774, 2022). "Interestingly, in one these patients the driver mutation in the tumor was identified to be in PTPN11, in the same gene that frequently acquires somatic mutations leading to HS in BMDs; and in two other FA patients, mutations in the tumors were in KRAS, also identified in HS of BMDs." (PMID 36292578, 2022). "Molecular profiling of the tumor revealed a loss-of-function NF1 mutation and a gain-of-function PTPN11 mutation, two convergent alterations in the MAPK pathway." (PMID 41853813, 2026). "Of note, the major phosphatases affected by PTEN were protein tyrosine phosphatases such as PTPN11, which has been extensively studied in tumor progression, highlighting the potential of PTEN in tyrosine phosphorylation." (PMID 41130297, 2025). "Arguing for a direct effect, conditional ablation of Ptpn11/SHP2 in CD4 T cells increased tumor progression in a melanocyte model." (PMID 40992926, 2025). "For example, knockout of Ptpn11 in myeloid cells increased T-cell activity, and SHP2 inhibition depleted pro-tumor macrophages." (PMID 40992926, 2025). "Of note was the fact that the telomerase reverse transcriptase (TERT) gene was differentially expressed (6.41 log2FC), with upregulation in the wild-type PTPN11 tumor samples." (PMID 40149290, 2025). "PTPN11 has been reported to participate in tumor immunotherapy resistance and has spawned several inhibitors, which can be applied in combination with anti-PD-1 and anti-PD-L1 therapies to improve immunotherapy efficacy." (PMID 38173048, 2024). "Her tumor tissue was sent for molecular testing and 2 mutations were detected in the FGFR1 and PTPN11 genes." (PMID 38903142, 2024).
tumor (continued). "MF targeted PTPN11, promoting cell cycle arrest and cell apoptosis, and consequently exerting effective anti-tumor activity." (PMID 37892971, 2023). "Two patients received long‐term TMZ chemotherapy before surgery, and mutations in the SHh (PTCH1) and PI3K/AKT signaling pathways (AKT1, PIK3CA, PTPN11) were detected in two tumor tissues (Patients 24 and 27)." (PMID 37533228, 2023). "Here, we applied genomic DNA sequencing to NF1-derived tumors and identified additional genetic alterations in PTPN11 (encoding Src homology region 2 domain-containing phosphatase-2 (SHP)-2) and BRAP associated with NF1 tumor malignancy." (PMID 35625983, 2022). "The results revealed that PTPN11 was remarkably related to the invasion levels of tumor-related fibroblasts and endothelial cells in most cancers, particularly in COAD, HNSC, LUAD, LUSC, and PAAD." (PMID 35802774, 2022). "Mechanistically, PTPN11 deletion attenuates CSF-1 receptor signaling, which depletes pro-tumor M2 macrophages while increasing anti-tumor M1 macrophages." (PMID 35957898, 2022). "According to the previous reports, a variety of intracellular events are regulated by PTPN11, including mitogenic activation, tumor cell proliferation, invasion, metastasis, apoptosis, senescence, and differentiation of multiple cell types." (PMID 35802774, 2022). "For example, only the occipital tumor region showed amplification of the EGFR locus, whereas a PTPN11 missense mutation and ERRFI1 homozygous deletion were exclusively in the parietal tumor region." (PMID 36114166, 2022). "Several researches have shown PTPN11 is essential for controlling immune cell activities in the tumor environment." (PMID 35802774, 2022). "Collectively, our study strongly suggests PTPN11 is a viable prognostic and therapeutic target for tumor." (PMID 35802774, 2022). "The results showed that stromal tumor-infiltrating lymphocytes (TILs) percent and the expression levels of CD44, B2M, PTPN11, and TRIM74 were associated with DFS in NPC patients." (PMID 36107539, 2022). "PTPN11, involved in the regulation of tumor and immune cell signaling, is a critical modulator of PD-1 and B and T lymphocyte attenuator (BTLA) immune checkpoint pathways and promising drug target in tumor immunotherapy." (PMID 35957898, 2022). "Genomic DNA sequencing allowed us to identify additional genetic alterations including mutations in the PTPN11 (encoding SHP-2) and BRAP genes that were associated with enhanced NF1-related tumor malignancy." (PMID 35625983, 2022). "More importantly, PTPN11 inhibitors combined with immunotherapies, such as anti-PD-1/L1, would reverse immunosuppression in the tumor microenvironment (TME) and potentiate the systemic antitumor effect in NSCLC cancer." (PMID 35957898, 2022). "A significant association was found between the genetic alteration levels of PTPN11 and some tumor predictions." (PMID 35802774, 2022). "According to the current research, how PTPN11 expression related to the invasion of tumor-related fibroblasts and endothelial cells was investigated." (PMID 35802774, 2022). "The tumor-suppressive role of PTPN11 in HCC is mediated through the IκB kinase/NF-κB (IKK/NF-κB) pathway through promoting IL-6-stimulated Stat3 activation." (PMID 35057034, 2022). "PTPN11 inhibition has been suggested to increase the levels of intratumoral CD8+ T cell and tumor-associated B cell to enhance the anti-tumor immunity." (PMID 35802774, 2022). "Oversignaling through this cascade is therefore enhanced by both the PTPN11 and the FGFR1 variant, likely representing two hits in the tumor progression." (PMID 35778969, 2022). "Nevertheless, a small number of PTPN family members exert more specific functions, for instance, PTPN11 as a tumor promoter whereas PTPN13 as a tumor suppressor in almost all cancers." (PMID 35957898, 2022). "The PTPN11 missense mutation identified in the present study induced pathological MEK activation and promoted tumor malignancy." (PMID 35625983, 2022).
tumor (continued). "For example, lncRNA LINC00673 inhibits tumor progression via reinforcing the interaction of PTPN11 with PRPF19 and facilitated STAT1-dependent antitumor response." (PMID 34322379, 2021). "PTPN11, encoding SHP2, which has been found to be a tumor suppressor in several cancer models, was found to be downregulated in tumor MF." (PMID 34831413, 2021). "In a study of more than 10,000 cases from 33 cancer types, high tumor expression of a germline variant in an oncogene (AR, MET, RET, CBL, and PTPN11) was found in 33 patients." (PMID 32295625, 2020). "Cytogenetic profiling with NGS showed nonsynonymous mutation p.E69K affecting the PTPN11 gene (SHP2), homozygous loss of CDKN2A at 9p21, and a tumor mutational burden of 26%." (PMID 32979930, 2020). "Downstream to SHP-2, MAPK and PI3K/AKT pathways are also potential targets for neoplasms with mutated PTPN11 and KRAS, and for which several FDA-approved inhibitors are currently available." (PMID 31277422, 2019). "PhenylHydrazonoPyrazolone Sulfonate 1 (PHPS1) was identified as a specific inhibitor of protein tyrosine phosphatase Shp2 (PTPN11), which is a positive regulator of growth factor signal as the one of the key mechanisms in carcinogenesis and tumor progression." (PMID 29890785, 2018). "This was accompanied by a hotspot activating missense mutation in PTPN11, two inactivating frameshift mutations in the NF1 tumor suppressor gene, and an inactivating frameshift mutation in the ATRX tumor suppressor gene." (PMID 28699883, 2017). "We detected an extraordinary level of tumor heterogeneity, with microclonal (mutant allele fraction <0.10) KRAS, NRAS, FLT3, and/or PTPN11 hotspot mutations evident in 31/57 (54.4%) patients." (PMID 27683039, 2016). "It is reported that the hyperactivation and misregulation of PTPN11 played an oncogenic role in various tumor types, especially germinal center derived lymphoma." (PMID 25944695, 2015). "To further explore the effect of rs199618935 on the expression of PTPN11, we used different genotypic HCC tissue samples as well as their adjacent non-tumor tissues to examine PTPN11 expression." (PMID 25198338, 2014). "Further studies confirmed the tumor suppressor roles of PTPN11 in HCC tumorgenesis and decreased PTPN11 expression has been shown to be a prognostic marker in HCC." (PMID 25198338, 2014). "Although PTPs generally act as tumour suppressors, PTPN11 has been identified as the first PTP oncogene." (PMID 20700123, 2010). "We have specifically identified a tumour-suppressive miRNA (miR-489) and found its direct target (PTPN11)." (PMID 20700123, 2010). "Of the 18 HS tumor samples, 14 contained PTPN11 activating mutations, and four dogs had no PTPN11 variant." (PMID 40149290, 2025). "According to this study, PTPN11/SHP2 may have a tumor-suppressive function in HCC that is driven by inflammation." (PMID 38504984, 2024). "An important question is whether PTPN11 inhibitors exert their anti-tumour function solely via effects on cancer cells or whether they also influence the immune response to tumours." (PMID 38334623, 2024). "The tyrosine phosphatase SHP2, encoded by the oncogene PTPN11, an early identified proto‐oncoprotein, has been extensively studied regarding its functions in supporting the malignant behaviors of tumor cells and inflammation immune regulation." (PMID 38247197, 2024).
tumor (continued). "In addition, several studies have shown that PTPN11 can also play an unexpected tumor suppressor role in HCC, implying that PTPN11 possesses dual roles in tumorigenesis." (PMID 36660927, 2023). "Both classifications exclude JMML from the category of overlap neoplasms, since JMML is a pediatric-onset entity with germline predisposition, typically characterized by the presence of germline PTPN11, CBL, and NF1 mutations and by predominantly myeloproliferative features." (PMID 37370785, 2023). "Moreover, the genetic removal of PTPN11 within tumor cells led to an increased presence of MHC class I molecules in co-culture scenarios." (PMID 38001644, 2023). "Overall, we proved that MF could exert an excellent anti-tumor effect through regulating PTPN11, which provides a theoretical basis for its clinical application." (PMID 37892971, 2023). "Src homology-2-containing protein tyrosine phosphatase 2 (SHP2), encoded by the PTPN11 gene, plays a critical role in the tumor microenvironment by regulating T cell activation, as well as polarization, phagocytosis, anti-inflammatory cytokine expression of macrophages." (PMID 37781354, 2023). "Meanwhile, PTPN11 encodes the Src homology 2 domain–containing protein phosphatase 2 (SHP-2), which mediates cell responses to various growth factors, hormones, and cytokines and is crucial for the migration and invasion of fibroblasts and tumor cells." (PMID 38060535, 2023). "LINC00673 is also clarified to suppress tumor progression by enhancing the binding of pre-mRNA processing factor 19 (PRPF19) to protein tyrosine phosphatase non-receptor type 11 (PTPN11), subsequently promoting PRPF19-mediated ubiquitination and degradation of PTPN11." (PMID 38174069, 2023). "To verify this, we constructed PTPN11-overexpressing cells to explore whether MF performs its anti-tumor effect by suppressing PTPN11." (PMID 37892971, 2023). "In addition, H3-K27 FGFR1MUT tumours presented often other hits in the MAPK pathway with NF1 (13/31; 42%) or PTPN11 in (3/22; 13.6%) as the topmost mutated genes." (PMID 38066305, 2023). "To further investigate whether the inhibition of PTPN11 was required for the anti-tumor efficacy of MF, we constructed stable PTPN11-overexpressing cells." (PMID 37892971, 2023). "Additionally, Zheng has announced that lncRNA LINC00673 serves as a tumor suppressor by accelerating the ubiquitination of oncogene PTPN11 via binding to miRNA-1231 and competing for the endogenous RNA (ceRNA) mechanism." (PMID 36186449, 2022). "Also, the phosphorylation levels of Y542 and Y580 of PTPN11 were remarkably lower in tumor tissues of LUAD." (PMID 35802774, 2022). "We identified missense mutations of BRAP (c.1109G > C, p.Gly370Ala) and PTPN11 (c.1508G > T, p.Gly503Val) in the tumor-derived subclones but not in the parental sNF96.2-GFP cells." (PMID 35625983, 2022). "Consequently, we examined the relationship between PTPN11 expression and tumor-infiltrating immune cells in fibroblasts and endothelial cells related to cancer." (PMID 35802774, 2022). "Moreover, another experimental data has indicated that PTPN11 regulates the focal adhesion kinase activity through dephosphorylating pTyr397 to maintain the lamellipodia persistence to promote tumor cell migration." (PMID 35802774, 2022). "We pinpoint the dLED characteristic of the NRAS gene, meaning that if a tumor has NRAS mutated a treatment that targets NRAS itself would be the best option to reduce their tumorigenicity, whereas if it is NRAS wild-type, a PTPN11 inhibition would be a better recommendation." (PMID 35805023, 2022).